RPS26P6 (ribosomal protein S26 pseudogene 6)
Gene: Processed pseudogene on chromosome 8 (100,895,771 to 100,896,118, forward strand). Ensembl gene ENSG00000212994.
Diseases named in the same sentence as RPS26P6 in open-access papers:
RPS26P6 is named in the same sentence as 2 diseases in open-access papers, as found by Europe PMC text mining. Sharing a sentence is not in itself a finding about the gene and the disease. The quoted sentences say what the papers report.
ovarian carcinoma (1 paper, 2019). A malignant neoplasm originating from the surface ovarian epithelium. "All these findings indicated that RPS26P15, AC004057.1, RPS26P31, RPS26P6, RPS26P3 and RPS26P47 were the most potential pseudogenes in regulating hsa-miR-363-3p in ovarian cancer." (PMID 31794425, 2019). "Among 56 predicted pseudogenes, only 6 pseudogenes (RPS26P15, AC004057.1, RPS26P31, RPS26P6, RPS26P3 and RPS26P47) were significantly upregulated in cancer samples (compared to normal samples) and advanced stage of ovarian cancer (compared to early stage ovarian cancer)." (PMID 31794425, 2019).
cancer (1 paper, 2019). A tumor composed of atypical neoplastic, often pleomorphic cells that invade other tissues. "Finally, only 6 pseudogenes, RPS26P15, AC004057.1, RPS26P31, RPS26P6, RPS26P3 and RPS26P47 were significantly upregulated in cancer tissues when compared with normal controls." (PMID 31794425, 2019).